IL6R (interleukin 6 receptor)
Diseases named in the same sentence as IL6R in open-access papers (continued):
Sharing a sentence is not in itself a finding about the gene and the disease.
rheumatic diseases (5 papers, 2020 to 2025). "This appears to occur independent of IL6Rα function (a receptor targeted in many rheumatic diseases)." (PMID 41145914, 2025). "Tocilizumab (TCZ), an interleukin-6 receptor antagonist, is approved for treating rheumatic diseases and has demonstrated efficacy in managing refractory non-infectious uveitis (NIU)." (PMID 39570440, 2024).
ST Elevation Myocardial Infarction (5 papers, 2018 to 2025). A myocardial infarction that produces elevation in the ST segments of the ECG. "We evaluated the effect of the IL-6 receptor (IL-6R)-antagonist tocilizumab on the expression of the anaphylatoxin receptors in whole blood from non-ST-elevation myocardial infarction (NSTEMI) patients." (PMID 30258440, 2018). "In a recent study, the IL-6 receptor (IL-6R) antagonist tocilizumab reduced C-reactive protein (CRP) and percutaneous coronary intervention (PCI)-related troponin T (TnT) release in patients with non-ST-elevation myocardial infarction (NSTEMI)." (PMID 30258440, 2018).
amyloid A amyloidosis (4 papers, 2014 to 2021). "Anti-interleukin-6 receptor, tocilizumab (TCZ), has been shown to improve clinical symptoms of patients with AA amyloidosis, accompanied with regression of the amyloid deposition." (PMID 25197587, 2014).
aneurysm (4 papers, 2019 to 2023). Bulging or ballooning in an area of an artery secondary to arterial wall weakening. "Four studies testing the effect of IL-6 or IL-6R inhibition in two different aneurysm models were identified." (PMID 36289670, 2022). "Two studies reported that significantly smaller aneurysms developed after an IL-6 blocking antibody was administered in the elastase perfusion model and an IL-6R blocking antibody was given in the calcium chloride model." (PMID 36289670, 2022). "Similarly, in mice models in which AAA was induced with a subcutaneous infusion of angiotensin II and an injection of an anti-TGFβ antibody, a blockade of the IL-6R-using antibody administered three times a week significantly reduced the aneurysm rupture rate." (PMID 36289670, 2022). "Within the calcium chloride model, tail vein administration of 2 mg of an IL-6R blocking antibody, commencing one day prior to aneurysm induction and repeated at a dose of 0.25 mg intraperitoneally every week, reduced the size of the aneurysm that developed after 6 weeks compared to controls." (PMID 36289670, 2022).
cardiomyopathy (4 papers, 2018 to 2025). A disease of the heart muscle or myocardium proper. "Administration of anti–interleukin-6 receptor antibody attenuated the development of inflammation and cardiomyopathy in cardiomyocyte-specific Regnase-1–deficient mice." (PMID 31931613, 2020). "Upregulated DEGs were associated with pro-fibrotic signaling, such as TGF-β signaling-associated genes (TGFB1, LTBP1, ANKRD1) and other cardiomyopathy-related signaling, such as the MAPK cascade (ADRA1A, EGR1, IL6R)." (PMID 37084237, 2023). "Adeno-associated virus 9–mediated cardiomyocyte-targeted gene delivery of Regnase-1 or administration of anti–interleukin-6 receptor antibody attenuated the development of cardiomyopathy induced by severe pressure overload in wild-type mice." (PMID 31931613, 2020).
cervical carcinoma (4 papers, 2016 to 2024). A carcinoma arising from either the exocervical squamous epithelium or the endocervical glandular epithelium. "Meanwhile, IL-6 is one of the key activators of STAT3, so we treated it to cervical cancer cell lines to reveal the relationship among IL-6R/LYN/STAT3." (PMID 27690342, 2016). "Previous data from our group had shown that IL6R, JAK1/JAK2, and STAT3/STAT5b were dysregulated in locally advanced cervical cancer." (PMID 38891028, 2024). "For immunostimulator, SLC30A1 expression positively correlated with IL6R (Spearman: ρ = 0.204, P = 0.000345), TNFSF15 (Spearman: ρ = 0.355, P = 2.19e-10), NT5E (Spearman: ρ = 0.299, P = 1.16e-07), and PVR (Spearman: ρ = 0.236, P = 3.29e-05) in cervical carcinoma." (PMID 35154468, 2022).
chronic obstructive pulmonary disease (4 papers, 2017 to 2023). A chronic and progressive lung disorder characterized by the loss of elasticity of the bronchial tree and the air sacs, destruction of the air sacs wall, thickening of the bronchial wall, and mucous accumulation in the bronchial tree. "Inhibition of IL-6 (or IL-6R) may be a therapy for asthma, chronic obstructive pulmonary diseases (COPD), and other lung diseases." (PMID 29674943, 2018).
Cirrhosis (4 papers, 2015 to 2023). A chronic disorder of the liver in which liver tissue becomes scarred and is partially replaced by regenerative nodules and fibrotic tissue resulting in loss of liver function. "Here we found upregulated IL-6R mRNA and protein expression in liver tissues, PBMs and serum from hepatitis B-associated cirrhosis patients compared with hepatitis B associated fibrosis patients." (PMID 28953986, 2017). "First, expression of miR-30b was downregulated whereas IL-6R was upregulated in liver tissues and PBMs from hepatitis B associated-cirrhosis patients compared with hepatitis B-associated fibrosis patients, indicating that miR-30b negatively regulated IL-6R expression." (PMID 28953986, 2017). "Although a number of inflammatory cytokines and chemokines were differentially expressed in PoPH nuclei as compared to non-PoPH cirrhosis nuclei across multiple clusters, the strongest associations were for increased IL6R and IL4R expression and decreased IL32 expression in PoPH clusters." (PMID 37558836, 2023). "In addition, since IL-6R in serum mainly comes from PBMs, the increased IL-6R levels in serum may be induced by the higher IL-6R in PBMs from hepatic cirrhosis patients." (PMID 28953986, 2017). "The negative correlation between IL-6R and miR-30b in patients indicates that miR-30b may regulate IL-6R expression in hepatic cirrhosis." (PMID 28953986, 2017). "Upon detailed assessment, cytokine levels and cirrhosis etiology revealed that HBV-cirrhosis—regardless of antiviral therapy—had a 3-fold increase in IFN-γ, TRAIL and CXCL1 (GRO-α) levels and up to 3-fold decrease in MMP-2, CXCL12, IL2RA, IL-6Rα, CCL2 (MCP1) and CCL21 (6kine) levels." (PMID 36230823, 2022).
Cognitive impairment (4 papers, 2023 to 2025). Abnormal cognition is characterized by deficits in thinking, reasoning, or remembering. "IL-6 signaling disorders caused by mutations in the ligand-binding subunit of IL6R (IL6R gene) may also be the cause of psychiatric and cognitive disorders." (PMID 38646100, 2024). "Importantly, blocking IL-6R suppresses bone marrow B lymphopoiesis, cerebral Aβ pathology, microglial reactivity and cognitive impairments." (PMID 40962797, 2025). "In addition, the treatment of the IL-6 receptor (IL-6R) blocking antibody tocilizumab prior to an open tibia fracture reduced blood-brain barrier breakdown, enhanced hippocampus activation of microglia, and cognitive impairment." (PMID 37373482, 2023).
coronary atherosclerosis (4 papers, 2022 to 2024). Atherosclerosis of the coronary vasculature. "Several studies have suggested different SNPs in the IL-6/IL-6R were associated with several inflammatory cytokines and in relation to the susceptibility to coronary atherosclerosis." (PMID 36060677, 2022). "On the basis of genetic evidence, IL6R-related pro-inflammatory pathway seems to have a causal role in the pathogenesis of coronary atherosclerosis, and IL6R blockade could be a novel therapeutic approach for prevention of coronary atherosclerotic disease." (PMID 36060677, 2022). "The associations with coronary atherosclerosis and AAA were further driven by a lead coding variant in IL6R, rs2228145 (Asp358Ala)." (PMID 39563277, 2024).
endotoxemia (4 papers, 2016 to 2022). "Vascular endothelial breakdown triggered by upregulated IL-6 and its subsequent binding to IL-6R (i.e., the classical IL-6 signaling) contributes to endotoxemia-induced organ injury." (PMID 34065201, 2021). "As TNF-α can modulate endotoxin-induced upregulation of IL-1β and IL-6, we thus conjectured that the SEM18 peptide can decrease the endotoxemia-induced upregulation of IL-1β and IL-6 in plasma and lung tissues as well as the endotoxemia-induced bindings of IL-1β/IL-1R and IL-6/IL-6R in lung tissues." (PMID 35337084, 2022). "In the present study, the PLA data indicated that KCF18 could simultaneously inhibit more than 70% binding of TNF-α to TNFR1, more than 80% binding of IL-1β to IL-1R, and approximately 70% binding of IL-6 to IL-6R in the liver tissues of mice with endotoxemia." (PMID 34065201, 2021).
hepatitis B (4 papers, 2011 to 2022). "For example, elevated TGF-β in patients with hepatitis B might "tune" CD4+ T cells with increased sensitivity to IL-6R signaling through inhibition of SOCS3." (PMID 21639870, 2011).
HIV-1 infection (4 papers, 2007 to 2023). The type species of lentivirus and the etiologic agent of acquired immunodeficiency syndrome (AIDS). "The ratio of IL6R/IL6 was higher in our study which may be due to differences in gender and chronicity of HIV-1 infection." (PMID 37812611, 2023).
IgA nephropathy (4 papers, 2012 to 2026). "Transcriptomic-wide MR identified candidate genes across GN subtypes: RECQL, BRSK2, and MGP in acute GN; AFM, CFHR5, and EPHB2 in chronic GN; IL6R, MBL2, and PRSS3 in IgA nephropathy; and TIMP4, HCK, and PEAR1 in membranous nephropathy." (PMID 41990104, 2026).
intracerebral hemorrhage (4 papers, 2024 to 2026). A cerebrovascular disorder characterized by bleeding into one or both cerebral hemispheres including the basal ganglia and the cerebral cortex. "They found that IL‐4, CD14, IL‐6R, and MSR1 were associated with intracerebral hemorrhage and lesion counts on MRI, while TLR4, CD14, IL‐6R, and IGH were linked solely with lesion counts." (PMID 39654683, 2024). "In intracerebral hemorrhage (ICH), eCIRP further amplifies inflammation via the interleukin-6 receptor (IL-6R)/signal transducer and activator of transcription 3 (STAT3) signaling pathway." (PMID 41750206, 2026).
kidney transplant (4 papers, 2017 to 2020). A surgical procedure in which one or both kidneys from a donor are implanted into a recipient. "The first study in kidney transplant patients and experimental transplant models showed that anti-IL6R treatment affected the proportion Tfh cells and reduced B cell differentiation toward IgG-producing plasmablasts." (PMID 28373876, 2017). "Notably, SNPs in CASP1, CRP, IL6R, MYD88, and TLR2 have not been examined for their impact on acute rejection in kidney transplant recipients." (PMID 32153387, 2019).
liver disease (4 papers, 2015 to 2025). "The lower N‐BAL is likely related to a disproportionately greater N loss caused by the enhanced protein catabolism associated with inflammation in liver disease, as suggested by the increased plasma levels of IL‐6Rα, TNFRI, and TNFRII in BDL mice." (PMID 39971588, 2025). "LIG not only suppresses HCC malignancy but also blocks tumor-associated macrophage recruitment and M2 polarization by inhibiting YAP/IL-6-driven activation of IL-6R/STAT3 signaling 5, suggesting therapeutic utility even in advanced, transformation-prone liver diseases." (PMID 40860128, 2025). "In general, IL-6 binds to the interleukin-6 receptor (IL-6R), and the IL-6/IL-6R complex initiates glycoprotein 130 (gp130) for the activation of JAK/STAT, MAPK and PI3K/AKT, which is essential for the early onset of liver disease and the progression and maintenance of the regenerative process." (PMID 35955794, 2022).
lupus nephritis (4 papers, 2016 to 2025). Glomerulonephritis in the context of systemic lupus erythematosus. "Although a positive effect of IL‐6R blocking on lupus nephritis in a murine model has been described by another group 15, in our study no significant benefit of IL‐6R blockage on renal function could be demonstrated." (PMID 26739431, 2016). "C3-LHF1 associated with renal function and remission in lupus nephritis, and exhibited dual functions: inhibiting classical and lectin complement pathways and acting as a partial IL6ST (gp130) agonist, independent of IL6Rα." (PMID 41145914, 2025).
psoriatic arthritis (4 papers, 2016 to 2022). Joint inflammation associated with psoriasis. "A 78-year-old Japanese woman with psoriatic arthritis associated with rapid joint destruction was successfully treated with a second-line anti-interleukin-6 receptor agent." (PMID 36324145, 2022). "For example, TNFα-, IL-6R- and IL-1β-neutralizing bDMARDs work in RA, whereas IL-17A and IL-12/23-neutralizing bDMARDs are very efficient in psoriatic arthritis or spondyloarthritis." (PMID 34680530, 2021).
pulmonary diseases (4 papers, 2016 to 2022). "Both anti-IL-6R antibodies tocilizumab and sarilumab received black box warnings regarding the risks of serious infections for patients with pulmonary diseases, issued by the U.S. Food and Drug Administration." (PMID 33384605, 2020). "Similarly, there was a significant increase in the populations expressing IL-6R or IL-21R in patients with SSc compared to healthy donors but patients without pulmonary disease had a decreased proportion of B cells expressing IL-6R." (PMID 35860745, 2022).
renal fibrosis (4 papers, 2021 to 2025). A final common manifestation of a wide variety of chronic kidney diseases characterized by glomerulosclerosis and tubulointerstitial fibrosis. "In animal studies, mice treated with IL-6R antibodies were partially immune to renal fibrosis." (PMID 38152332, 2023). "Additionally, ADAM17 cleaves cell membrane IL‐6R, releasing soluble IL‐6R, which binds to IL‐6 forming complexes that act on gp130 protein on immune cell membranes, activating the intracellular JAK/STAT pathway to induce renal fibrosis." (PMID 40077919, 2025).
respiratory infection (4 papers, 2012 to 2023). "We lacked data for infectious events in the genetic studies; however, published evidence from candidate gene studies have not suggested an IL6R association with risk of respiratory infection." (PMID 22421340, 2012).
sarcoidosis (4 papers, 2020 to 2024). Sarcoidosis is a multisystemic disorder of unknown cause characterized by the formation of immune granulomas in involved organs. "Although IL-6 signalling is thought to be important in sarcoidosis aetiology, a small clinical trial of IL-6R inhibition showed null preliminary results." (PMID 38951047, 2024). "While few cases showed the efficacy of anti-interleukin-6 (IL-6) or IL-6 receptor (IL-6R) agents in refractory sarcoidosis, new-onset sarcoidosis during TCZ treatment has been described in five case reports." (PMID 34359324, 2021). "The possible futility of larger trials was supported by an MR analysis, which did not provide genetic support that IL-6R inhibition reduces risk of sarcoidosis." (PMID 38951047, 2024).
tuberculosis (4 papers, 2011 to 2023). A chronic, recurrent infection caused by the bacterium Mycobacterium tuberculosis. "Some showed that the expression ratio of Thl7 cells in tuberculosis patients didn’t vary significantly from those in the healthy, or it was even lower than in the healthy when accompanied by less expression of IL-6R of CD4 + T cells." (PMID 25089129, 2014). "Consistent with our previous finding in patients with tuberculosis, we found IL-6R expression on CD4+ T cells, but not plasma IL-6, correlated with the Th17 response in HBV infected individuals." (PMID 21639870, 2011). "However, unlike Mycobacterium tuberculosis antigens which down-regulated IL-6R expression on CD4+ T cells from patients with tuberculosis, HBV antigen (HBcAg) up-regulated IL-6R expression on CD4+ T cells from patients with CHB." (PMID 21639870, 2011).
ankylosing spondylitis (3 papers, 2016 to 2024). An autoimmune chronic inflammatory disorder characterized by inflammation in the vertebral joints of the spine and sacroiliac joints. "However, the clinical significance of the IL6R blockade for ankylosing spondylitis (AS) therapy remains controversial." (PMID 38835791, 2024). "In addition, in another 34-year-old Japanese male AS patient treated with IL6R antagonists, the patient's Bath Ankylosing Spondylitis Disease Activity Index (BASDAI) and Bath Ankylosing Spondylitis Functional Index (BASFI) decreased gradually from 3.3 to 0.4 and from 2.7 to 0.1, respectively." (PMID 38835791, 2024).
aortic stenosis (3 papers, 2015 to 2026). Aortic valve stenosis is a aortic valve disease caused by the incomplete opening of the aortic valve. "Wypasek and colleagues reported that IL-6R single nucleotide polymorphisms were associated with mean concentrations of C-reactive protein among patients with aortic stenosis." (PMID 26714766, 2015). "For example, the IL6R locus strengthens the link between inflammation and aortic stenosis beyond the previously identified IL6 locus." (PMID 41419685, 2026).
Burkitt lymphoma (3 papers, 2014 to 2024). A rare form of malignant mature B-cell non-Hodgkin lymphoma. "Recently, miR-197 was found to act synergistically with EBV-BART6-3p to reduce the expression of IL-6R, thereby compromising host immune defense in EBV-positive Burkitt Lymphoma." (PMID 29379474, 2017). "In particular, we analyzed the IL-6 receptor genes (IL-6Rα and IL-6ST), PTEN and WT1 expression for their possible relevance to Burkitt lymphoma." (PMID 24731550, 2014).
cognitive decline (3 papers, 2015 to 2021). "In an exploratory analysis, 3/83 proteins (SGOT, MCP-1, IL6r) were also found to be mildly associated with cognitive decline in MCI subjects over a 4-year period." (PMID 26284520, 2015). "However, in a sample of MCI subjects (n = 142) we found three proteins (SGOT, MCP-1, and IL-6r) were able to significantly predict cognitive decline." (PMID 26284520, 2015).
dry eye (3 papers, 2011 to 2022). "For the IL6R gene, the genotypic and allelic distribution of rs8192284 was different between the dry eye patients and the controls: CC genotype (p=0.017, OR=2.12) and C allele (OR=1.26)." (PMID 22128229, 2011). "Inflammation is also an important component of dry eye and polymorphisms in the proinflammatory cytokine genes IL-1β (SNP rs1143634) and IL-6R (SNP rs8192284) have been reported to associate with non-Sjogren dry eye symptoms in a Korean population." (PMID 25896684, 2015). "It is suggested that rs1143634 of IL1B and rs8192284 of IL6R act as susceptibility variations in Korean non-Sjogren dry eye patients." (PMID 22128229, 2011).
endometrial cancer (3 papers, 2022 to 2025). Primary or metastatic malignant neoplasm involving the endometrium (mucous membrane that lines the endometrial cavity). "In 12 lymph nodes (4 cancerous and 8 non‐cancerous), significantly higher adiponectin (p = 0.0002), leptin (p = 0.011), and IL6R (p = 0.009) expression was observed compared to endometrial cancer tissue." (PMID 40642843, 2025). "Concerning the receptors, IL6R and both TNF receptors were markedly upregulated in endometrial cancer tissue compared to the control sample." (PMID 40642843, 2025). "The marked upregulation of IL6R and TNF receptors (TNFRSF1A, TNFRSF1B) in cancer tissue compared to controls supports the notion that these cytokines and their signaling pathways are central to the development and aggressiveness of endometrial cancer." (PMID 40642843, 2025). "Using qRT‐PCR analysis, endometrial cancer tissues (n = 39) exhibited higher expression levels of adiponectin, leptin, IL6, TNFα, and their receptors, IL6R and TNFRSF1A/B, compared to the calibrator sample, which consisted of five pooled benign endometrial control samples." (PMID 40642843, 2025).